Y_RNA (Y RNA )
Gene: Miscellaneous RNA gene on chromosome 2 (112,579,484 to 112,579,584, reverse strand). Ensembl gene ENSG00000207383.
Homologues: Orthologues: chimpanzee Y_RNA (100% identical), macaque Y_RNA (97% identical), pig Y_RNA (87% identical), dog Y_RNA (86% identical), guinea pig Y_RNA (83% identical). Paralogues in human: Y_RNA (91% identical), RNY3 (90% identical), Y_RNA (90% identical), Y_RNA (89% identical), Y_RNA (88% identical), RNY3P1 (87% identical), RNY3P14 (87% identical), RNY3P9 (87% identical), Y_RNA (87% identical), Y_RNA (86% identical), RNY3P16 (85% identical), Y_RNA (85% identical), and 94 more.